GOLGA8Q (golgin A8 family member Q)
Tractability: No criterion of Open Targets' tractability assessment is met for any kind of drug.
Gene: Protein-coding gene on chromosome 15 (30,552,050 to 30,565,684, forward strand). Ensembl gene ENSG00000178115.
Gene Ontology:
Biological process: Golgi organization
Cellular component: cis-Golgi network; Golgi cis cisterna; Golgi cisterna membrane; Golgi apparatus
Genetic constraint (gnomAD): Loss-of-function variants: 0 observed, 0.97 expected, observed/expected ratio (o/e) 0, 90% interval 0 to 1.73. That is too few expected variants to judge how well the gene tolerates losing a copy. Missense variants: 2 observed, 11.47 expected, observed/expected ratio (o/e) 0.17, 90% interval 0.07 to 0.55. Synonymous variants: 0 observed, 3.6 expected, observed/expected ratio (o/e) 0, 90% interval 0 to 0.83.
Homologues: Orthologues: chimpanzee GOLGA8S (90% identical), mouse Golga2 (44% identical), dog GOLGA2 (43% identical), tropical clawed frog golga2 (33% identical), zebrafish golga2 (30% identical), Drosophila melanogaster GM130 (22% identical), Caenorhabditis elegans golg-2 (19% identical), rat Golga2l1 (5% identical). Paralogues in human: GOLGA8N (99% identical), GOLGA8O (99% identical), GOLGA8R (98% identical), GOLGA8M (92% identical), GOLGA8H (90% identical), GOLGA8J (90% identical), GOLGA8K (90% identical), GOLGA8T (90% identical), GOLGA8S (84% identical), GOLGA8F (79% identical), GOLGA8G (79% identical), GOLGA8A (66% identical), and 6 more.